SPAG17 (sperm associated antigen 17)
Description:
Component of the central pair apparatus of ciliary axonemes. Plays a critical role in the function and structure of motile cilia. May play a role in endochondral bone formation, most likely because of a function in primary cilia of chondrocytes and osteoblasts (By similarity). Essential for normal spermatogenesis and male fertility (By similarity). Required for normal manchette structure, transport of proteins along the manchette microtubules and formation of the sperm head and flagellum (By similarity). Essential for sperm flagellum development and proper assembly of the respiratory motile cilia central pair apparatus, but not the brain ependymal cilia (By similarity).
Synonyms: FLJ34497; PF6; RP4-776P7.2; CT143; SPGF55
Tractability: Antibody: its Gene Ontology location is reachable by antibodies, with medium confidence.
Gene: Protein-coding gene on chromosome 1 (117,953,590 to 118,185,228, reverse strand). Ensembl gene ENSG00000155761.
Subcellular location: Cytoplasm; Cytoplasm, cytoskeleton, flagellum axoneme; Cytoplasmic vesicle, secretory vesicle, acrosome; Golgi apparatus; Cytoplasm, cytoskeleton
Subcellular location (Human Protein Atlas): Mid piece; Principal piece; Equatorial segment
Gene Ontology:
Biological process: axonemal central apparatus assembly; epithelial cilium movement involved in extracellular fluid movement; intramanchette transport; manchette assembly; motile cilium assembly; spermatogenesis
Cellular component: acrosomal vesicle; axonemal central apparatus; cytoplasm; Golgi apparatus; manchette; cytoskeleton; extracellular region
Genetic constraint (gnomAD): Loss-of-function variants: 141 observed, 234.17 expected, observed/expected ratio (o/e) 0.6, 90% interval 0.52 to 0.69. The upper end of that interval is the gene's LOEUF score, 0.69, which puts it in group 2 of 6, group 1 being the genes least tolerant of losing a copy. Missense variants: 2,238 observed, 2,400.4 expected, observed/expected ratio (o/e) 0.93, 90% interval 0.9 to 0.96. Synonymous variants: 722 observed, 806.92 expected, observed/expected ratio (o/e) 0.89, 90% interval 0.84 to 0.95.
Homologues: Orthologues: chimpanzee SPAG17 (98% identical), macaque SPAG17 (95% identical), dog SPAG17 (80% identical), rabbit SPAG17 (80% identical), pig SPAG17 (75% identical), guinea pig SPAG17 (75% identical), mouse Spag17 (74% identical), rat Spag17 (71% identical), tropical clawed frog spag17 (40% identical), zebrafish spag17 (14% identical).
Diseases named in the same sentence as SPAG17 in open-access papers:
SPAG17 is named in the same sentence as 20 diseases in open-access papers, as found by Europe PMC text mining. Sharing a sentence is not in itself a finding about the gene and the disease. The quoted sentences say what the papers report.
asthenozoospermia (3 papers, 2018 to 2024). "Twin males with severe asthenozoospermia were described with a homozygous missense mutation in the SPAG17 gene." (PMID 29690537, 2018). "Recently, twins from a consanguineous marriage with severe asthenozoospermia were found to have a predicted damaging homozygous missense mutation (R1448Q) affecting the C-terminus of the SPAG17 protein." (PMID 29690537, 2018). "A homozygous mutation (R1448Q) in SPAG17 gene was identified in an asthenozoospermia patient, which suggested SPAG17 may be a new pathogenic gene causing asthenozoospermia." (PMID 31234269, 2019).
male infertility (3 papers, 2018 to 2025). The inability of the male to effect fertilization of an ovum after a specified period of unprotected intercourse. "In comparison, HPO encodes phenotype annotations of human SPAG17, orthologous to mouse Spag17, at a much coarser level of detail, using terms such as ‘Reduced sperm motility’ (HP:0012207) and ‘Male infertility’ (HP:0003251)." (PMID 40963406, 2025). "We have also identified putatively causal variants in seven genes validated as aetiological factors of male infertility, such as SPAG17, REC114, TERB1, DNAH6, ADGRG2, MAMLD1, and USP26." (PMID 39678461, 2024).
primary ciliary dyskinesia (3 papers, 2020 to 2022). A rare, genetically heterogeneous, primarily respiratory disorder characterized by chronic upper and lower respiratory tract disease. "Whole-exome sequencing identified this primary ciliary dyskinesia only (Pcdo) allele to be a nonsense mutation (c.5236A>T) in the Spag17 coding sequence creating a premature stop codon (K1746*)." (PMID 32988999, 2020). "More recently, SPAG17 variants were reported to cause primary ciliary dyskinesia in human patients." (PMID 32988999, 2020). "DNAI1 anomalies have been previously associated with TGA, while the central pair associated protein SPAG17 has been associated only with Primary Ciliary Dyskinesia (PCD)." (PMID 36140829, 2022). "Interestingly, a cluster formed by 12 elements, including WDR63, DNAH3, DNAI1, TTC18, SPAG17, TTC25, and CCDC113, was found to be a cluster related to primary ciliary dyskinesia and COPI-independent Golgi-to-ER (Cluster 10689, STRING False Discovery Rate: 1.0–12)." (PMID 36140829, 2022).
Infertility (2 papers, 2021 to 2025). "Of interest, some candidates related to sperm and infertility were identified, containing MORC1, TDRD9, ZFYVE21, ADGRB3, SPAG17, CKB, and WDR3, which may have effects on sperm motility and fertilization." (PMID 33477586, 2021).
asthma (1 paper, 2021). "SPAG17 has been linked to the immune and lung related outcomes, as it has been shown to be associated with asthma susceptibility." (PMID 33868365, 2021).
tumor (2 papers, 2021 to 2025). "We found more than one TA was expressed per tumor, and seven TAs (GPC3, IGF2BP3, NOL4, NR6A1, PKB, PRAME, and SPAG17) were detected in multiple tumors." (PMID 40894019, 2025).
cancer (1 paper, 2018). A tumor composed of atypical neoplastic, often pleomorphic cells that invade other tissues. "Meanwhile, the three identified PCGs—DDX51, SPAG17, and NUMA1—have been well studied for their associations with cancers." (PMID 29373522, 2018). "Moreover, SPAG17 is predominantly expressed in cancer-testis antigens and might serve as a target for cancer immunotherapy." (PMID 29373522, 2018).
respiratory disease (1 paper, 2023). "In mice, Spag17- deficient mice lacking ciliary central pair microtubules and thus resembling a PCD cilia defect were found to have immotile airway cilia and PCD-like respiratory disease as well as skeletal abnormalities." (PMID 37555648, 2023).
SPAG17 also shares sentences with these, for which no sentence is quoted: infection (4 papers); lung cancer (2); melanoma (2); angioedema (1); Azoospermia (1); endometriosis (1); lung disease (1); malaria (1); nasopharyngeal carcinoma (1); proctitis (1); prostate carcinoma (1); viral infection (1).